DRC1 (dynein regulatory complex subunit 1)
Description:
Component of the nexin-dynein regulatory complex (N-DRC) a key regulator of ciliary/flagellar motility which maintains the alignment and integrity of the distal axoneme and regulates microtubule sliding in motile axonemes (By similarity). Plays a critical role in the assembly of N-DRC and also stabilizes the assembly of multiple inner dynein arms and radial spokes. Coassembles with DRC2 to form a central scaffold needed for assembly of the N-DRC and its attachment to the outer doublet microtubules.
Synonyms: C2orf39; CCDC164; MGC16372; FLJ32660; CILD21; SPGF80
Tractability: Small molecule: a structure with a bound ligand is known. Antibody: its Gene Ontology location is reachable by antibodies, with medium confidence.
Gene: Protein-coding gene on chromosome 2 (26,401,920 to 26,456,717, forward strand). Ensembl gene ENSG00000157856.
Subcellular location: Cytoplasm, cytoskeleton, cilium axoneme; Cytoplasm, cytoskeleton, flagellum axoneme
Subcellular location (Human Protein Atlas): Nucleoplasm; Primary cilium transition zone
Gene Ontology:
Molecular function: protein binding
Biological process: axonemal dynein complex assembly; cilium-dependent cell motility; cilium movement; flagellated sperm motility; regulation of cilium movement; axoneme assembly; protein-containing complex assembly
Cellular component: axonemal nexin link; axoneme; axonemal dynein complex; cilium; cytosol; sperm flagellum
Genetic constraint (gnomAD): Loss-of-function variants: 76 observed, 106.07 expected, observed/expected ratio (o/e) 0.72, 90% interval 0.59 to 0.87. The upper end of that interval is the gene's LOEUF score, 0.87, which puts it in group 3 of 6, group 1 being the genes least tolerant of losing a copy. Missense variants: 873 observed, 928.02 expected, observed/expected ratio (o/e) 0.94, 90% interval 0.89 to 1. Synonymous variants: 335 observed, 352.6 expected, observed/expected ratio (o/e) 0.95, 90% interval 0.87 to 1.04.
Gene-disease validity (ClinGen):
ClinGen rates the evidence that DRC1 causes each of these diseases.
primary ciliary dyskinesia 21 (autosomal recessive): Definitive.
Homologues: Orthologues: chimpanzee DRC1 (99% identical), macaque SELENOI (96% identical), dog DRC1 (84% identical), pig DRC1 (80% identical), guinea pig DRC1 (78% identical), rabbit DRC1 (78% identical), rat Drc1 (76% identical), mouse Drc1 (76% identical), tropical clawed frog drc1 (52% identical), zebrafish drc1 (42% identical), Drosophila melanogaster CG10958 (26% identical). Paralogues in human: DRC2 (12% identical).
Diseases named in the same sentence as DRC1 in open-access papers:
DRC1 is named in the same sentence as 21 diseases in open-access papers, as found by Europe PMC text mining. Sharing a sentence is not in itself a finding about the gene and the disease. The quoted sentences say what the papers report.
primary ciliary dyskinesia (10 papers, 2015 to 2025). A rare, genetically heterogeneous, primarily respiratory disorder characterized by chronic upper and lower respiratory tract disease. "Previous studies have reported that mutations in DRC1 largely result in primary ciliary dyskinesia, morphological abnormalities of the sperm flagella, and male infertility." (PMID 35872895, 2022). "Analysis of copy number variation revealed a biallelic deletion in the dynein regulatory complex subunit 1 (DRC1) gene in 21 patients, which accounted for 49% of the primary ciliary dyskinesia patients in whom a disease‐causing gene was found." (PMID 31960620, 2020). "Specifically, mutations in DRC1, DRC2/CCDC65, and DRC4/GAS8 are associated with ciliary motility disorders, leading to primary ciliary dyskinesia (PCD)." (PMID 41460250, 2025). "DRC1 (MIM: 615288) encodes a central component of the nexin-dynein complex that regulates the assembly of ciliary dynein and is associated with primary ciliary dyskinesia (MIM: 615294)." (PMID 29290337, 2018). "Among 32 genes in which defects lead to primary ciliary dyskinesia, six (Dnaic2, Ccdc40, Armc4, Ccdc164/DRC1, Rsph9, Ccdc11) are strongly downregulated in Rfx2-/- testes at both time points, and three others only at P30 (Ccdc65, Zmynd10, Ccno)." (PMID 26162102, 2015).
male infertility (4 papers, 2021 to 2025). The inability of the male to effect fertilization of an ovum after a specified period of unprotected intercourse. "Their defects cause situs inversus, hydrocephalus, and male infertility, emphasizing the importance of DRC1 and DRC2 for N-DRC assembly onto the ciliary axoneme and proposing an N-DRC assembly model." (PMID 40089458, 2025). "Collectively, these data suggest that mutations in DRC1 cause a spectrum of clinical presentations involving defects in motile cilia function, and that variants in DRC1 are a novel high confidence cause of male infertility." (PMID 34089056, 2021). "In summary, we herein identified a novel DRC1 mutation that causes MMAFand male infertility, and we found that genetic background profoundly influences thephenotypic manifestation of this mutation." (PMID 34169321, 2021). "Additionally, DRC1 defects also result in male infertility, in line with previous research showing that DRC1 mutations cause multiple morphological abnormalities of sperm flagella (MMAF) and male infertility due to failed N-DRC assembly in humans and mice." (PMID 40089458, 2025). "Herein, we identified twohomozygous DRC1 variants in human patients that were associated withmultiple morphological abnormalities of the sperm flagella (MMAF) and male infertility.Drc1−/−, Drc1R554X/R554X andDrc1W244X/W244X mice on the C57BL/6 background suffered frompre-pubertal mortality." (PMID 34169321, 2021).
situs inversus (3 papers, 2020 to 2025). A congenital condition in which there is complete right-to-left reversal of the position of the major thoracic and abdominal organs (that is, they are arranged in a mirror image of the normal positioning). "As PCD-related genes, Drc1−/−, Drc2−/−, and Drc4−/− mice also exhibited situs inversus, which implicates nodal cilia." (PMID 40089458, 2025). "In the other studies, none of the patients with a DRC1 variant had situs inversus, as in our patient, which suggests that DRC1 somehow do not affect the nodal cilia." (PMID 36856967, 2023). "Additionally, a small percentage of Drc1−/−, Drc2−/− and Drc4−/− mice exhibited situs inversus." (PMID 40089458, 2025).
ciliopathies (2 papers, 2016 to 2023). "In summary, scaffold proteins (DRC1, DRC2, DRC4) play a vital role in assembling the N-DRC since any defect in these subunits can cause severe ciliopathies." (PMID 37714832, 2023).
Hydrocephalus (2 papers, 2023 to 2025). Hydrocephalus is an active distension of the ventricular system of the brain resulting from inadequate passage of CSF from its point of production within the cerebral ventricles to its point of absorption into the systemic circulation. "As we previously reported in the Drc1−/− mice, we identified hydrocephaly in nearly half of the Dnali1−/− mice, which may have resulted from ventricular ciliary dysfunction." (PMID 36792588, 2023).
infertile (2 papers, 2023). "As far as we know, this study is the first to report two infertile PCD women carrying a DRC1 variant." (PMID 36856967, 2023). "Our findings suggest that the DRC1 null variant leads to PCD associated with infertility, likely caused by defects in axoneme from Fallopian tube cilia." (PMID 36856967, 2023). "We identified a homozygous nonsense variant in the DRC1 gene (NM 145038.5:c.352C>T (p.Gln118Ter)) in the female patient with PCD and infertility that fit the model of autosomal recessive genetic transmission." (PMID 36856967, 2023). "Other cases involving DRC1 variants, but not infertility, have been reported, primarily in Asia, where DRC1 variants are common." (PMID 36856967, 2023).
congenital heart disease (1 paper, 2022). A heart disease that is present at birth. "Among these, only compound heterozygous mutation, c.T470G (p.L157R) and c.A1622G (p.D541G), in the DRC1 gene have been reportedly related to congenital heart disease and are the most likely causative in our patient." (PMID 35872895, 2022).
COVID-19 (1 paper, 2022). A disease caused by infection with severe acute respiratory syndrome coronavirus 2. "Considering genes related to pulmonary diseases (PD), we identified two variants in the DRC1 gene significantly associated with COVID-19 severe outcome." (PMID 35955824, 2022). "The logistic regression on 7423 SNPs and short indels for genes related to pulmonary diseases identified two variants significant in COVID-19 severe outcome, in Dynein Regulatory Complex Subunit 1 (DRC1) with ORs of 0.56 and 1.71." (PMID 35955824, 2022).
ependymoma (1 paper, 2023). A WHO grade II, slow growing tumor of children and young adults, usually located intraventricularly. "Present results showed that DRC1, dynein regulatory complex subunit 1, expression is associated with short survival, which was partially in line with a previous study reporting that circRNAs derived from DRC1 were upregulated in ependymomas." (PMID 36836422, 2023). "Genes such as DRC1, which are known to be relevant to myeloid cells and to be upregulated in ependymomas, are worth further investigation for their prognostic value." (PMID 36836422, 2023).
female infertility (1 paper, 2023). Diminished or absent ability of a female to achieve conception. "Here we firstly report a DRC1 null variant associated with female infertility in a patient with a clinical diagnosis of PCD and idiopathic infertility." (PMID 36856967, 2023). "Together, this work demonstrates strong evidence for the association of DRC1 and its pathogenic variant c.352C>T with the PCD phenotype and female infertility." (PMID 36856967, 2023). "Here we report, for the first time, a DRC1 variant associated with female infertility in the Iberian Peninsula, and firstly report the immunolocalization of DRC1 in human nasal cells, both in healthy individuals and in a PCD patient carrying a DRC1-null variant." (PMID 36856967, 2023).
glioma (1 paper, 2023). A benign or malignant brain and spinal cord tumor that arises from glial cells (astrocytes, oligodendrocytes, ependymal cells). "Inflammatory microglial cells, dendritic cells, myeloid cells, and glioma stem cells were highly expressed in GBM tissue, and ACP7, EPPK1, PCDHA8, RHOD, DRC1, ZIC3, and PRLR were significantly associated with survival." (PMID 36836422, 2023).
DRC1 also shares sentences with these, for which no sentence is quoted: cancer (2 papers); alcoholic liver diseases (1); asthma (1); genetic disorder (1); infection (1); Joubert syndrome (1); pulmonary diseases (1); respiratory infections (1); Senior-Loken syndrome (1); tumor (1).